IL18 (interleukin 18)
Diseases named in the same sentence as IL18 in open-access papers (continued):
Sharing a sentence is not in itself a finding about the gene and the disease.
cancer (continued). "Further, it will be interesting to perform in vitro as well as in vivo studies to explore the possible link between YAP1 and IL‐18 for a better understanding of cancer progression." (PMID 34196131, 2022). "IL-18 has also been proven to promote the occurrence and development of cancer by inhibiting anti-metastasis and immune surveillance mediated by NK cells and T cells." (PMID 36276078, 2022). "Novel IL-15-based therapies have combined it in preclinical studies with other immunotherapeutic agents, such as monoclonal antibodies (rituximab, alemtuzumab), CD40 agents, cancer vaccines, and other cytokines (IL-12, IL-18, and IL-21)." (PMID 35529882, 2022). "Regarding the interferon family, while IFN-β and IP-10 were not significantly altered, IFN-γ was significantly increased in both solid and haematological malignancy patients, and IL-18 (also called IFN-γ-inducing factor) only in the later cancer group." (PMID 34830872, 2021). "NLRP3 inflammasome activation, caspase-1 activation, release of IL-1β and IL-18 pro-inflammatory cytokines and gasdermin D-mediated pyroptotic cell death are important mechanisms involved in inflammation-induced cancer." (PMID 34452150, 2021). "The combination of IL-27 followed by IL-18 (27→18) successfully reduced cancer cell viability, with significant effects in cell culture and in an immunocompetent mouse model." (PMID 34209203, 2021). "Of these 23, the most significantly enriched and relevant were the interleukin‐18 (IL‐18) signalling pathway as well as the senescence and autophagy in cancer signalling pathway, with the latter corresponding to 14 upregulated genes." (PMID 34180119, 2021). "IL-18 had been shown to exert potential immunosuppressive effects in cancer by increasing expression of programmed cell death-1 (PD-1) on activated mature NK cells." (PMID 33718235, 2021). "Once activated, NLRP3 inflammasome induces the release of pro-inflammatory cytokines IL-1β and IL-18, which can contribute to cancer progression." (PMID 34681768, 2021). "It was reported that high concentrations of serum IL-1β and IL-18 are strictly correlated to poor prognosis of cancer patients." (PMID 34211462, 2021). "Specifically, IL-18 can activate NK cells to eliminate cancer cells and therefore is a potential target for cancer immunotherapy." (PMID 33660570, 2021). "The IL-18 role in cancer is explained as a dual-edge sword, as its secretion of IFN-γ acts as an antitumor mechanism." (PMID 34840991, 2021). "IL-1α, IL-1β, and IL-18 have been investigated in many types of cancer with both pro- and anti-tumorigenic functions mediated by different cells." (PMID 33840390, 2021). "It has been shown that cytokines, especially IL-6, IL-18 and TNFα, are involved in both inflammaging and different chronic conditions such as heart disease, kidney disease and cancer." (PMID 34444668, 2021). "At present, IL-18 has been studied as a novel treatment approach and immune checkpoint therapy to significantly improved cancer treatment." (PMID 34627252, 2021). "With the help of the enzyme-linked immunosorbent assay (ELISA) technique, they have found high expressions of IL-18, thus suggesting the involvement of this cytokine in cancer growth." (PMID 33015196, 2020). "Among them, the expression of AIM2/ASC/IL-18, MyD88, DAI, DHX36, and DDX60 were associated with cancer stages." (PMID 31949493, 2020). "Activation of NLRP3 also leads to release of active interleukin-18 (IL-18), which has been found to mediate painful conditions such as muscle pain, cancer-induced bone pain and neuropathic pain." (PMID 32973552, 2020). "Specifically, overexpression of LncRNA ADAMTS9 promoted LDH release, and increased NLRP3 and ASC expression levels in cancer tissues, and promoted IL-18 and IL-1β expressions in mice serum." (PMID 32516127, 2020).
cancer (continued). "IL18 demonstrated a significant depot by group interaction effect (P = 0.0009) with increased expression in the VAT of both cancer groups compared with control (CWS P = 0.02, CC P = 0.0001)." (PMID 32232960, 2020). "IHC staining indicated that Pin1 expression was positively correlated with IL‐18 expression in PDAC tissues in 39 patients diagnosed with PDAC in our cancer centre." (PMID 32347623, 2020). "This connection between NLRP3, bowel diseases, and cancer is multifaceted and the resulting inflammation and cytokine secretion (namely IL-18) can be protective against tumor growth." (PMID 32098318, 2020). "IL-18 induces programmed cell death protein 1-dependent immunosuppression in cancer, and IL-1β is one of the most important pro-inflammatory mediators involved in immune resistance." (PMID 33096896, 2020). "To investigate the function of IL‐18 in Pin1‐induced cancer progression, we transfected the IL‐18 siRNA into the MIA PaCa‐2 cells stably overexpressed Pin1." (PMID 32347623, 2020). "Next, several studies have shown that IL-18 has anti-cancer or pro-cancer effects depending on the doses." (PMID 31731729, 2019). "These anti-cancer effects of high-dose IL-18 is consistent with our data, which indicate that higher expression of IL-18 has a better prognosis." (PMID 31731729, 2019). "A growing number of studies have proven the regulatory roles of inflammasome-dependent cytokines (IL-1β and IL-18) in cancer development." (PMID 31492049, 2019). "Numerous studies have investigated the role of IL-18 in cancer, with both pro- and anti-tumorigenic functions identified." (PMID 31231372, 2019). "IL-18 shows anticancer activity in different pre-clinical models of cancer immunotherapy through the activation of NK and/or T cell responses." (PMID 31492049, 2019). "IL-18 is a representative proinflammatory cytokine and it is known to have both anti-cancer and pro-cancer properties depending on the host environment." (PMID 31731729, 2019). "Several members of this family, such as IL-1β and IL-18, have been extensively investigated in cancer with both pro- and anti-tumorigenic functions ascribed to these cytokines." (PMID 31231372, 2019). "Taken together, these results suggest that IL18 mRNA expression has different prognostic effects in different cancer types." (PMID 31731729, 2019). "Serum IL-18 and NO activity can be used as a marker for evaluating disease activity in patients with cancer breast." (PMID 31554361, 2019). "The first attempts to administer IL-18 to cancer patients showed that its toxicity was generally mild-to-moderate." (PMID 30717382, 2019). "Clinical studies have been conducted to assess the therapeutic efficacy of IL-18 in cancer patients." (PMID 31492049, 2019). "Inflammasomes exert an important function in releasing interleukin- (IL-) 1β and IL-18, which in turn prompt inflammatory response to clean up cancer cells." (PMID 31737176, 2019). "NO levels were significantly higher values in the three cancer breast patients groups compared to control group.IL18 was significantly high in the metastatic group." (PMID 31554361, 2019). "A lot of studies have suggested that IL-18 shows anti-cancer effects in combination with other cytokines including IL-12 and IL-15 as results of inducing T cell proliferation and NK cell activation in vitro." (PMID 31731729, 2019). "In short, the OS and DFS results show that high NLRP3 inflammasome expression (NLRP3/IL-18/ IL-1β/ASC) in LSCC cancer tissues forecasts a poor outcome compared to low NLRP3 inflammasome expression (NLRP3/IL-18/IL-1β/ASC) in cancer tissues (P < 0.05)." (PMID 31312615, 2019). "We also demonstrated here that IL-15/IL-18/IL-27-stimulated NK cells retained high perforin expression and underwent some target-dependent degranulation and that target cancer cells experienced caspase-dependent apoptosis." (PMID 31277710, 2019).
cancer (continued). "As well as being a regulator of immune responses, IL-18 also participates in the immune escape of cancer cells, inflammatory responses, and autoimmune responses depending on the host environment." (PMID 31731729, 2019). "In particular, the anti-cancer effects of IL-18 accompanied by the activation of NK cells and T cells are often manifested in high doses of IL-18 in combination with IL-2 or IL-12." (PMID 31731729, 2019). "Here, we describe two recent theories on the beneficial roles of IL-18 in protecting against cancer." (PMID 30717382, 2019). "A recent report confirmed the anti-cancer effect of IL-18 released from macrophages in response to commensal fungi on colitis-associated cancer." (PMID 30717382, 2019). "Second, IL-18 can inhibit the recognition of cancer cells by immune cells, enhancing cancer cell adherence to the vascular wall, increasing the production of angiogenic and growth factors, and providing a pro-metastatic microenvironment." (PMID 30925760, 2019). "Although it is still at the stage of animal experiments, a new treatment method using IL-18 for cancer treatment has been studied." (PMID 30717382, 2019). "The purpose of this research is to identify the potential role of IL18 and NO and their relation to oxidative stress in the development of cancer breast." (PMID 31554361, 2019). "Of interest, gene deficiency or blockade of IL-18, OPN, or thrombin ameliorated the progression of RA and cancer, partly due to inhibiting angiogenesis, although it has yet to be determined how these mediators contribute to pathologic angiogenesis." (PMID 29559970, 2018). "VEGF is known to stimulate IL-18 production, which in turn, promotes cancer cell migration, proliferation, angiogenesis and decreases cancer cell susceptibility to lymphocyte mediated cytotoxicity." (PMID 30517191, 2018). "Our results show that treatment of A549 cancer cells with 4-HBA induces the transcription of (amongst others) caspase-1, IL1β, and IL18 encoding genes." (PMID 29352134, 2018). "IL-18 has the ability to inhibit the recognition of cancer cells by immune cells, increase cancer cell adherence to the microvascular wall, induce the production of angiogenic and growth factors, and promote a pre metastatic microenvironment." (PMID 30365491, 2018). "Because IL-18 is considered a possible novel clinical treatment for some conditions, such as cancer immunotherapy, assessment of adverse effects are required." (PMID 29514661, 2018). "Activated NLRP3 inflammasome induces the maturation of its effector cytokine IL-18 which functions in the development of cancer." (PMID 29312552, 2017). "While the inflammatory cytokine interleukin-18 (IL-18) is known to activate natural killer (NK) cells, its precise role in cancer is controversial." (PMID 28415798, 2017). "On the other hand, the immunomodulatory of inflammasome activities, particularly IL-18, can be harnessed for immunotherapy against cancer." (PMID 28955343, 2017). "Due to a potential role of IL-18 in cancer progression and metastasis, an IL18BP-Fc has been developed to antagonize the effects of IL-18." (PMID 28391240, 2017). "Clinically, the measurement of IL-1β, IL-18, IL-6, and MIC-1/GDF-15 correlates with the risk of carcinoma and the prognosis of established cancer." (PMID 27429614, 2016). "Nevertheless, NK cells treated with IL-18 in combination with IL-12 or triple therapy with IL-12, IL-15 and IL-18 resulted in strongly augmented NK cell degranulation and proliferation in cancer studies." (PMID 27821119, 2016). "The activated AIM2 inflammasome in macrophages promotes the proteolytic cleavage and secretion of pro-inflammatory cytokines (IL-1β and IL-18) through the activation of caspase-1, leading to cell senescence, apoptosis and preventing cancer progression." (PMID 27806724, 2016). "Interleukin-18 (IL-18) has exhibited interesting anti-cancer properties especially when combined with IL-12." (PMID 27483370, 2016).
cancer (continued). "Previous researches illustrated that the elevated serum IL-18 played an important role in a variety of cancers, and a similar function of IL-33 is still under debate." (PMID 27340318, 2016). "Both of these cell types have been reported to exhibit a high level of IL-18 expression that is related to cancer progression, including proliferation, metastasis, and angiogenesis." (PMID 27941650, 2016). "Contradictorily, recent studies have shown that, in addition to the antitumor activity of IL-18 in the immune system, IL-18 can exert pro-cancer effects when produced by cancer cells, acting to promote cell proliferation and migration." (PMID 25780408, 2015). "Pro-IL-18 is also cleaved by caspase-1 into its mature form and has been reported to play both beneficial and detrimental roles in the progression of cancer." (PMID 26378020, 2015). "The role of IL-18 in regulating NK cell activity in healthy individuals and especially in cancer patients is still very controversial." (PMID 25889680, 2015). "The difference between our patient cohort and the TCGA database parallels the confounding literature regarding IL-18 and cancer." (PMID 26378020, 2015). "On the one hand, IL-18 induces T helper type 1 (Th1) immune response, which is generally regarded as the immune reaction that acts against malignant tumors." (PMID 24963217, 2014). "The variability in NLRP3- and IL-18-mediated effects in different cancers highlights the complexity in NLR circuits and suggests that any broad implications regarding NLR intervention in tumorigenesis should be carefully investigated." (PMID 25071785, 2014). "IL-18 is a multifunctional cytokine that has a critical role in ovarian physiologic function, inflammation, and immune response to cancer." (PMID 24963217, 2014). "In our previous study, it was shown that IL-18 levels were associated with disease progression (TNM staging) and also elevated in tobacco exposed patients of carcinoma." (PMID 25177683, 2014). "“Reducing IL-1beta and IL-18 production by inhibition of ICE-1 is one promising strategy...” in cancer treatment that was outlined already in 2001 by Randle's group in München." (PMID 23594434, 2013). "Because immune stimulating effects of IL-18 have also antineoplastic properties, it was tempting to propose IL-18 as a novel adjuvant therapy against cancer." (PMID 24130810, 2013). "IL-18 has been administered to humans for the treatment of cancer in order to increase the activity and expansion of cytotoxic T-cells." (PMID 24115947, 2013). "In humans an increase in IL-18 is correlated with various types of cancer including ovarian carcinoma, head and neck squamous carcinoma, breast cancer, and others." (PMID 24273542, 2013). "Along with IL-1β, the cytokine IL-18 is also cleaved by caspase-1 into its mature form and plays both beneficial and detrimental roles in the progression of cancer." (PMID 24273542, 2013). "The NLRP3 inflammasome, a protein complex controlling maturation of important pro-inflammatory cytokines interleukin (IL)-1β and IL-18, is also involved in tumorigenesis and metastasis of various cancers." (PMID 24223129, 2013). "Higher expression of IL-18 is detected in various cancer cells compared with normal control, and IL-18 is able to induce angiogenesis, migration, proliferation and immune escape." (PMID 24066061, 2013). "IL-18 serum levels have been reported to be elevated in a variety of cancers compared with control group." (PMID 24130810, 2013). "The analysis also confirmed down-regulation of CCL2, IL18, and up-regulation of Wnt7b genes in macrophages grown under co-culture conditions with cancer cells." (PMID 22353646, 2012). "Additional investigation will be required to discover a niche for IL-18 in cancer immunotherapy strategies." (PMID 24213115, 2011). "Recent years have seen a number of cytokines, including GM-CSF, IL-7, IL-12, IL-15, IL-18 and IL-21, enter clinical trials for patients with advanced cancer." (PMID 24213115, 2011).
cancer (continued). "On the other hand, downstream targeting of IL-1β and IL-18 could be less selective overall but more effective in suppressing the pro-inflammatory signals that promote cancer progression." (PMID 40141358, 2025). "In addition, PM2.5 exposure induces aryl hydrocarbon receptor (AhR)-dependent transcription of transmembrane serine protease 2 (TMPRSS2) and interleukin-18 (IL-18), further promoting cancer progression in EGFR-mutant cells." (PMID 39578555, 2025). "Moreover, given the enthusiasm for IL-18 as a cancer immunotherapy due to its capacity to elicit a type 1 immune response, these findings also offer insight into potential off-target effects." (PMID 40935830, 2025). "In other scenarios, IL-1β and IL-18 are known to enhance T cell-mediated anti-cancer immunity." (PMID 40141358, 2025). "In cancer-induced bone pain, microglia in the spinal cord could maintain advanced-phase cancer pain in female rats by producing IL-18 expression to enhance synaptic transmission." (PMID 40332543, 2025). "These indicate that IL-18 can participate in chronic pain induced by cancer and SLE." (PMID 40332543, 2025). "Next, we grouped them into cytokines associated with pre-cancer or the initiation stage of HCC (IL-6, TGF-β, MCP-1, FGF2, IL-2, IL-8, IL-12p40, IL-12p70, IL-18, IP-10, TNF-α, and IFN-γ), the early stage of HCC (OPN, GDF-15, RANTES, and VEGFA), and the advanced stage of HCC (IL-10, and MIP-3)." (PMID 41219858, 2025). "IL11 and IL18 are cytokines involved in hematopoiesis, cancer metastasis, and inflammation." (PMID 39484639, 2024). "IL-2, IL-12, IL-15, IL-18, and IL-21 could promote NK cells entry into S and G2/M phases of the cell cycle in cancer patients or healthy subjects, and thus have been used to induce ex vivo NK cell proliferation." (PMID 39286242, 2024). "Additional Phase I clinical studies (NCT05989204 and NCT06287528) were performed in patients with Relapsed or Refractory Acute Lymphoblastic Leukemia to evaluate IL-18 secretion by anti-CD19 CAR T cells engineered to constitutively secrete this cytokine in patients with CD19-positive cancers." (PMID 39769266, 2024). "IL‐18 and IL‐18BP can regulate the immune response to both cancer and microbial infections." (PMID 39188114, 2024). "Cancer is yet an additional example in which IL-18’s dual nature is exhibited." (PMID 39769266, 2024). "Conversely, in conditions where immune responses are suppressed, such as cancer, strategies to inhibit IL-18BP and boost IL-18 activity might be more appropriate." (PMID 39769266, 2024). "However, the implication of plasma IL‐18 as a prognostic biomarker in cancer has been a subject of debate and merits further investigations." (PMID 37681284, 2024). "Notably, cisplatin downregulated the toll-like receptor signalling pathway, TLR 2/4, along with IL-18, which is required for killer T-cell activation, potentially indicating an attempt by cancer cells to avoid immune destruction." (PMID 38674023, 2024). "Additionally, Viaud, Sophie is dedicated to studying the immunosuppressive role of IL-18 in cancer and how anti-PD-1 antibodies can exert clinical effects in human malignant tumors." (PMID 39885985, 2024). "However, prolonged exposure of T cells to IL-1β and/or IL-18 resulted in suppressive effects on T cells and was detrimental to the cancer-bearing organism." (PMID 39796680, 2024). "The pivotal role of IL-12 and IL-18 in cancer is also supported by previous studies." (PMID 38785507, 2024). "NLRP3 inflammasome is composed of NLRP3, apoptosis-associated speck-like protein containing CARD (ASC) and effector pro-caspase-1, and can affect the occurrence and development of IBD and even cancer via regulating the maturation, secretion, and pyroptosis of IL-1β and IL-18." (PMID 38650627, 2024). "Nowadays, engineered IL-18 is a promising biologic that could enhance innate and adaptive immunities and avoid the immune barrier for cancer immunotherapy." (PMID 39684709, 2024).